PPARA (peroxisome proliferator activated receptor alpha)
Diseases named in the same sentence as PPARA in open-access papers (continued):
Sharing a sentence is not in itself a finding about the gene and the disease.
Sepsis (continued). "As a consequence of PPARα malfunction, FFAs are no longer oxidized which leads to the ectopic deposition of lipid storages in liver and kidney after sepsis and thereby causes lipotoxicity and tissue damage." (PMID 37006237, 2023). "Because crosstalk of transcription factors in physiology and pathology is a commonly observed phenomenon, we hypothesized that HIF1α and/or HIF2α might play a role in the PPARα and GR dysfunction during sepsis." (PMID 37006237, 2023). "Besides GR and PPARα dysfunction, sepsis is also characterized by fundamental shifts in tissue metabolism in combination with a decreased tissue perfusion and edema." (PMID 37006237, 2023). "However, GR and PPARα become dysfunctional during sepsis, and so the amounts of glycogen, WAT, and muscle mass rapidly decline, while blood levels of FFAs, glycerol, amino acids (AAs), and lactate increase." (PMID 37006237, 2023). "Since HIFs interfere with the expression of multiple important metabolic enzymes, and since HIFs use transcriptional co-factors, such as p300, which are also essential for the function of GR and PPARα, we aimed to investigate the role of HIF1α and HIF2α in more detail during sepsis, in the liver." (PMID 37006237, 2023). "Sepsis is also characterized by a PPARα dysfunction in the liver." (PMID 37006237, 2023). "Thus, we concluded that H2 decreases BBB permeability to protect against brain dysfunction in sepsis; this effect is mediated by PPARα and its regulation of ABC efflux transporters." (PMID 37474902, 2023). "Also, sepsis leads to disruption of fatty acid oxidation, which is reflected in the downregulation of peroxisome proliferator-activated receptor alpha (PPARα)." (PMID 36212144, 2022). "Mice with a deletion of PPARα in their hepatocytes display an increased mortality upon sepsis." (PMID 36552845, 2022). "The role of PPARα in human sepsis patients has already been investigated." (PMID 36552845, 2022). "In murine sepsis, reduced mRNA expression of PPARα and its targets involved in FFA β-oxidation could indeed be linked to a reduced capability of liver explants to metabolize palmitic acid ex vivo, as measured with the Seahorse technology." (PMID 36552845, 2022). "Together these data reveal PPARα as an interesting new target for sepsis." (PMID 36552845, 2022). "Preventing PPARα dysfunction with pemafibrate, however, reduces sepsis mortality." (PMID 36552845, 2022). "PPARα targets related to FFA β-oxidation are especially reduced in the livers of sepsis pigs, which might explain the increased FFA levels in plasma and lipid accumulation in their livers." (PMID 36552845, 2022). "Moreover, clinical trials are warranted to validate the therapeutic applicability of this axis (i.e., PPARα resistance–FFA increase–lipotoxicity) in human individuals with sepsis." (PMID 36552845, 2022). "Thus, it is possible that these rapid decreases in the expression of key genes, including PPARα and PPARδ, are important in driving the reductions in cardiac fatty oxidation and myocardial dysfunction in sepsis." (PMID 34575939, 2021). "Taken together, PPARα expression increased fatty acid oxidation and subsequently supported the hyperdynamic cardiac response early during sepsis or pressure-overloaded heart failure, which may prevent morbidity and mortality." (PMID 34445672, 2021). "Multiple studies have reported altered expression of PPARα during sepsis." (PMID 33616039, 2021). "Furthermore, during sepsis, WT hearts showed a decrease in PPARα and other FAO genes’ mRNA expression, and this reduction was more dramatic in Ppara-null mouse hearts." (PMID 34445672, 2021). "In addition, antagomir-21 restored PPARα expression and attenuated sepsis-induced liver injury, whereas PPARα antagonist GW6471 blocked the inhibitory effect of antagomir-21 on liver injury." (PMID 33424957, 2020).
Sepsis (continued). "Moreover, pemafibrate pretreatment protects mice against sepsis through enhanced hepatic PPARα function, which in turn improves metabolic and inflammatory parameters, and reduces organ dysfunction." (PMID 31916705, 2020). "Activation and inactivation of PPARα before the onset of sepsis confirm the importance of this transcription factor, and more importantly, activation of residual PPARα after the onset of sepsis can lead to a significant protection and survival." (PMID 31916705, 2020). "We believe our findings may have a major impact on the sepsis research field and could pave the way to new therapeutic interventions in sepsis as our data using a novel PPARα agonist are promising." (PMID 31916705, 2020). "Hepatic PPARα function and lipid metabolic pathways are dysregulated in polymicrobial sepsis." (PMID 31916705, 2020). "However, the knowledge on dysregulation of PPARα signaling and metabolic pathways during sepsis is far from complete and warrants further study in both animal models of sepsis and septic patients." (PMID 31916705, 2020). "We found that administration of pemafibrate, a novel selective PPARα modulator (SPPARMα) with improved selectivity, potency, and safety profile, improved PPARα function and reduced the metabolic dysregulation during sepsis." (PMID 31916705, 2020). "The role of hepatic PPARα in liver dysfunction during sepsis has hardly been explored." (PMID 31916705, 2020). "This study showed that the mir-21/PPARα pathway might be an interesting new strategy for sepsis treatment." (PMID 33424957, 2020). "Our corroborative clinical data indicate that similar PPARα dependent processes may be operative in human sepsis." (PMID 31102342, 2019). "The progressive loss of HNF4α activity in sepsis is associated with diminished chromatin binding of HNF4α, thereby reducing H3K27 acetylation and chromatin accessibility and causing the downregulation of many genes coding for proteins, among which nuclear receptors such as PPARα." (PMID 40904458, 2025). "However, glucocorticoid receptors, peroxisome proliferator-activated receptors (PPARα), and other key factors of lipid metabolism are inactivated in the pathological state of sepsis, which leads to the accumulation of harmful metabolites in the liver, such as free fatty acids and lactic acid." (PMID 39019343, 2024). "The mechanism by which PPARα is downregulated in sepsis remains unknown." (PMID 39261648, 2024). "Furthermore, we have investigated the functional role of HIF1α and/or HIF2α during sepsis in more detail via hepatocyte-specific HIF1α and/or HIF2α knock-out mice with a focus on their role in the annihilation of the transcriptional function of GR and PPARα." (PMID 37006237, 2023). "Thus, based on previous research, our study explored the potential protective role of H2 in brain damage in sepsis and whether the effects were due to the upregulation of PPARα to ABC efflux transporters." (PMID 37474902, 2023). "This might indicate that HIF1α contributes to the decline in PPARα and its signaling in sepsis." (PMID 37006237, 2023). "While this work did not investigate the mechanisms and factors driving alterations in hepatic lipid metabolism during sepsis, we hypothesize altered regulation of transcription factor peroxisome proliferator-activated receptor alpha (PPARα) to be play a critical role." (PMID 33616039, 2021). "In addition, the liver PPARα expression was found to be disturbed during sepsis." (PMID 33424957, 2020). "Furthermore, in the mouse liver, PPARα is a key factor in the metabolic adaptation to sepsis." (PMID 32708786, 2020). "Moreover, miRNA‐dependent regulation of PPARs has been described in metabolic diseases and could play a role in PPARα downregulation during sepsis." (PMID 31916705, 2020). "However, the mechanisms behind the PPARα regulation during sepsis remain largely unknown and are possibly varying between tissues." (PMID 31916705, 2020).
Sepsis (continued). "Prior studies have shown that PPARα signaling is downregulated in the myocardium during endotoxemia and CLP sepsis." (PMID 40626362, 2025). "The observed downregulated expression of PPARα and its co-activator PGC-1α in the acute phase of sepsis further supports an acute suppression of mitochondrial oxidation." (PMID 39821755, 2025). "Key metabolic transcription factors PPARα and PGC-1α were downregulated in acute, but upregulated in prolonged, sepsis (p ≤ 0.05 for both)." (PMID 39821755, 2025). "In this study, hepatocyte-specific HNF4α knockout mice displayed reduced expression and activity of PPARα, diminished IL6-induced acute phase response, and increased mortality from sepsis." (PMID 40061452, 2025). "Peroxisome proliferator-activated receptor alpha (PPARα), the master regulator of hepatic lipid metabolism and FAO, is significantly downregulated during sepsis." (PMID 41439929, 2025). "Mice treated with the PPARα antagonist, GW6471, together with sepsis induced by cecal ligation and puncture (CLP), displayed a significant rise in mortality." (PMID 39261648, 2024). "Our data suggest that the loss of hepatic HNF4α impairs the expression of several other nuclear receptors besides PPARα, including RXRα, FXR, CAR, AR and LXRα, and therefore has a broad downstream impact in sepsis." (PMID 39261648, 2024). "In patients died from sepsis, the expression levels of COMT and PTGS2 were significantly elevated, PPARA and PPARG were significantly decreased." (PMID 38641695, 2024). "We further examined the expressions of rate-limiting enzyme CPTI and related molecules PPARα and PPARγ as well as its cofactors PGC-1α and PGC-1β to determine FAO levels in WT and TREM2–/– sepsis mice." (PMID 39405126, 2024). "However, the role of HNF4α in sepsis and in the regulation of PPARα in sepsis remains unknown." (PMID 39261648, 2024). "Our data further suggest that during sepsis, FFA metabolism is changed, mainly at the level of FFA oxidation and lipoprotein secretion, and that PPARα expression is downregulated, both of which can be attributed to the LOF of hepatic HNF4α." (PMID 39261648, 2024). "Cannabinoids exert in vivo protective and anti-inflammatory effects in LPS-induced sepsis by mechanisms that rely on CB1- and PPARα-mediated autophagy induction." (PMID 34548620, 2022). "The synthetic cannabinoid WIN55212-2 exhibits in vivo protective and anti-inflammatory effects in LPS-induced sepsis by mechanisms depending on CB1- and PPARα-mediated autophagy induction and also promotes the generation of FOXP3+ Tregs." (PMID 34548620, 2022). "In addition, the study compared wild-type mice with PPARα deletion (PPARα -/-) mice and showed that in sepsis, PPARα -/- mice had a relative deficiency of nonlipid substrates and an excess of lipid substrates that they were unable to utilise, as indicated as the cause of their increased mortality." (PMID 34300048, 2021). "For this purpose, we used antagomir-21 to inhibit miR-21 expression in murine sepsis model and detected the levels of proinflammatory cytokines (TNF-α, IL-1β, and IL-6), liver injury markers (AST, ALT), and PPARα expression." (PMID 33424957, 2020). "Notably, the expression of PPARα and PGC-1α was suppressed during the acute phase of sepsis, but increased to supranormal levels in prolonged sepsis." (PMID 39821755, 2025). "Similar results have been found in sepsis in which the metabolic and inflammatory responses to bacterial infection were impaired in the absence of PPARα, which leads to an enhancement in mortality due to bacterial sepsis." (PMID 38633246, 2024). "The decreased expression of PPARα in Hnf4aLiver-KO mice has been documented, yet the relation between HNF4α and PPARα in sepsis has not yet been described." (PMID 39261648, 2024). "So, we hypothesized that PBA may induce a series of beneficial metabolic changes through the regulation of the immune microenvironment of sepsis by PTGS2, COMT and PPARA." (PMID 38641695, 2024).
Sepsis (continued). "The acute lack of PPARα and GR function during sepsis makes the liver key in sepsis, not only because this organ produces acute phase proteins." (PMID 37006237, 2023). "As PPARα is involved in FFA oxidation, the LFC of all genes involved in FFA oxidation based on gene ontology analysis (GO:0019395), and which depend on PPARα for their expression, were compared between sham and sepsis samples." (PMID 36552845, 2022). "The absence of PPARα causes a reduction in cardiac performance and FAO in sepsis." (PMID 40872501, 2025). "It would thus be of great interest to investigate whether hepatic PPARα stimulation with pemafibrate or GW7647, well known PPARα agonists, in the absence of HIF1α in hepatocytes during sepsis might be able to restore PPARα functioning and reduce lipotoxicity." (PMID 37006237, 2023). "Altogether, we conclude that HIF proteins are not involved in the appearance of GCR in liver during sepsis and that HIF1α in hepatocytes of septic animals might be involved in the reduced PPARα signaling." (PMID 37006237, 2023). "Within the context of the lack of food intake in sepsis and the consequent SR, the liver is confronted with high levels of FFAs, glycerol and gluconeogenic AAs, which require PPARα and GR, respectively, to be properly transformed into acetyl-CoA, KBs, and glucose." (PMID 37006237, 2023). "Importantly, gene expression of PPARα and downstream genes was also increased after pemafibrate in livers of CLP mice 24 h post‐sepsis initiation, with many genes reaching expression levels close to those seen in vehicle‐treated sham mice (only Acsl1 and Slc25a20 are shown, Fig EV3C and D)." (PMID 31916705, 2020). "Since the PPARα coding gene PPARα is a PPARα‐responsive gene itself, we hypothesized that pretreatment of mice with the PPARα agonist pemafibrate might increase PPARα gene expression, improve PPARα function, and protect mice during the CLP‐induced peritonitis sepsis model." (PMID 31916705, 2020). "We hypothesized that the lack of transcriptional activity of PPARα during sepsis is due to decreased PPARα expression levels." (PMID 31916705, 2020). "Therefore, we wanted to investigate whether HIF1α and HIF2α expression in hepatocytes contributes to the GCR and PPARα failure present in sepsis, as this has not been studied before." (PMID 37006237, 2023). "The PPARα knockout mice could not maintain appropriate immune functions against sepsis shock." (PMID 32908637, 2020). "HNF4α and PPARα are known regulators of Nr1i3 transcription, but their link with CAR in sepsis has not been described." (PMID 40904458, 2025).
liver disease (83 papers, 2006 to 2026). "In the liver, KRT79 is controlled by PPARA and is highly correlated with liver injury, making it a potential diagnostic marker for human liver disease." (PMID 38017403, 2023). "Alterations of PPARα expression or activity were associated with a variety of human pathologies such as obesity, liver diseases, inflammation, and cancers." (PMID 28167956, 2017). "Administration of PPARα agonists improves liver disease in mice caused by chronic alcohol exposure." (PMID 31920652, 2019). "PPARs are potential regulators of metabolism and inflammation, where the isoform PPARα is indispensable in the regulation of hepatic inflammation and is considered a key molecule for addressing metabolic dysfunction-associated steatotic liver disease pathogenesis." (PMID 39768147, 2024). "Additionally, SREBPs and Pparα may be key genes to elucidate the pathogenesis of liver diseases relevant to Phb1 deficiency in terms of lipid metabolism." (PMID 34539442, 2021). "Our results suggest that treatment of PPARα agonists results in the production of oxidative stress and increased peroxisome proliferation, thus providing a better understanding of mechanisms underlying PPARα agonist-induced hepatic disorders and hepatocarcinomas." (PMID 17118139, 2006). "In humans, PPARA gene expression negatively correlates with the progression of steatotic liver disease." (PMID 41373582, 2025). "In various liver disease models, the administration of a PPARα agonist has been shown to not only reduce lipid accumulation but also alleviate fibrosis." (PMID 41159141, 2025). "The effects of PPARα following intermittent fasting are shown to ameliorate the progression of steatotic liver disease to fibrosis and even hepatic cell carcinogenesis." (PMID 39796579, 2024). "Current research demonstrates that activated PPARα is currently undergoing clinical trials in liver disease." (PMID 38004166, 2023). "Taken together, these results demonstrate that hepatic Krt79 is a PPARA target gene and that KRT79 can be used as a biochemical or histological diagnostic biomarker for human liver diseases." (PMID 36796223, 2023). "In this review, we aim to provide a comprehensive overview of the roles of PPARα in lipid metabolic diseases, such as liver diseases, diabetes-related diseases, growth disorders, and even cancers, in the context of metabolic diseases." (PMID 38004166, 2023). "We uncovered declined FBXW7 and PPARA as features of advanced NASH and revealed significant correlations between FBXW7 and PPARA in multiple human liver diseases." (PMID 37914694, 2023). "Although PPARγ is more weakly expressed in the liver than PPARα, it is essential for liver function, and the DNA methylation status of the Pparg gene has been identified as a marker of liver disease progression." (PMID 34638914, 2021). "Genetic risk factors for liver disease (NAFLD) were associated with lipid and glucose metabolism, including peroxisome proliferator-activated receptor-alpha (PPARA), PPARG, LIPIN1, and insulin receptor substrate 1 (IRS1)." (PMID 33466498, 2021). "In this context, the role of bilirubin in protecting from the development of liver disease, by activating the PPARα that is ultimately responsible for fatty acid transport and peroxisomal and mitochondrial fatty acid β-oxidation has been proposed." (PMID 33260451, 2020). "miRNAs-dependent alterations of PPARα signaling are reported by numerous studies to contribute to the onset of liver diseases such as nonalcoholic fatty liver disease (NAFLD), chronic diseases associated with viral infections (HBV, HCV), or hepatic cancers." (PMID 28167956, 2017). "Our findings unveil a novel therapeutic trajectory that harnesses a single microbial metabolite to activate PPARα-mediated tissue repair/renewal pathways across the gut-liver axis, offering a promising biologic therapeutic for treatment of metabolic and inflammatory liver diseases." (PMID 40793786, 2025).